CYP1B1 (cytochrome P450 family 1 subfamily B member 1)
Diseases named in the same sentence as CYP1B1 in open-access papers (continued):
Sharing a sentence is not in itself a finding about the gene and the disease.
congenital glaucoma (37 papers, 2008 to 2025). "Previous studies have verified the contribution of CYP1B1, a gene that causes congenital glaucoma with high IOP, to juvenile and adult-onset POAG in various populations including Asian, Australian and Middle Eastern ethnicities." (PMID 28264060, 2017). "Studies examining the correlation between the histological alterations in the aqueous outflow pathways in congenital glaucoma and the different mutations in the CYP1B1 gene are scarce and difficult to conduct." (PMID 28448622, 2017). "According to our results, a previous report described an association of severe or moderate angle abnormalities with specific CYP1B1 mutations in congenital glaucoma patients." (PMID 28448622, 2017). "Although CYP1B1 gene alterations have been identified as the main known genetic cause of congenital glaucoma, the underlying mechanisms remain poorly understood." (PMID 28448622, 2017). "Myocilin (MYOC) is a causative gene for POAG and cytochrome P450, 1B1 (CYP1B1) for congenital glaucoma." (PMID 20142848, 2010). "Another patient (PCG 022) with the CYP1B1 p.L24R mutation only had bilateral buphthalmos with raised intraocular pressure." (PMID 19536304, 2009). "No similar reports are available for FOXC1, but studies in mice demonstrated that Foxc1+/- heterozygotes as well as animals homozygous for mutations in congenital glaucoma genes Cyp1b1 and Angpt have abnormally formed trabecular meshwork and/or Schlemm’s canal." (PMID 36284357, 2022). "Notably, the only target that was found to be differentially expressed in heterozygous compared to affected homozygous patients, CYP1B1, was reported to be associated with congenital glaucoma." (PMID 33193710, 2020). "FOXC2, PITX2 and CYP1B1 variants identified in congenital glaucoma patients." (PMID 30657791, 2019). "Finally, the CYP1B1 gene, which has been implicated in congenital glaucoma as well as PA, is located in 2p22." (PMID 21738392, 2011). "Mutations in the cytochrome P4501B1 (CYP1B1) gene are a predominant cause of congenital glaucoma." (PMID 20057908, 2009). "Mutations in CYP1B1 have been identified in numerous studies of congenital glaucoma." (PMID 19148291, 2009). "Mutations in Cytochrome P450 (CYP1B1) are a predominant cause of congenital glaucoma." (PMID 19536304, 2009). "Studies of pathogenic sequence variants of CYP1B1 in different populations may contribute to a better insight into the molecular pathogenesis of congenital glaucoma." (PMID 19536304, 2009). "Biallelic variants in CYP1B1 are the most common cause of autosomal recessive PCG and often linked to corneal opacities presenting as edema, Haab’s striae or buphthalmos." (PMID 41155148, 2025). "Linkage studies of familial and congenital glaucoma have shown the existence of genes with a significant effect on the disease, such as MYOC (myocilin) and OPTN (optineurin) for familial primary open-angle glaucoma (POAG) and CYP1B1 for congenital glaucoma." (PMID 38333055, 2024). "We did not identify pathogenic or likely pathogenic variants in other genes known to cause congenital glaucoma, including rare variants (allele frequency <0.001) in ANGPT1, CPAMD8, CYP1B1, MYOC, LTBP2, PITX2, SVEP1, and TEK." (PMID 36453543, 2022). "Mutations in the CYP1B1 gene have been found in a single family with ARS, and while a relatively common cause of congenital glaucoma is some populations, mutations in CYP1B1 appear to be an extremely rare cause of ARS." (PMID 34576164, 2021). "CYP1B1 (cytochrome P450, family 1, subfamily b, polypeptide 1) is a gene suggested to be involved in congenital glaucoma." (PMID 31212881, 2019). "In this study, we have analyzed for the first time the CYP1B1 genotype activity and the microscopic and clinical phenotypes in congenital glaucoma." (PMID 28448622, 2017).
congenital glaucoma (continued). "Using consanguineous pedigrees from Saudi Arabia and Turkey, defects in the cytochrome P4501B1 (CYP1B1) gene coding for a protein that is a member of the cytochrome P450 family were found in individuals affected with congenital glaucoma." (PMID 21217896, 2010). "In the present study we screened all coding exons of CYP1B1 in 23 unrelated congenital glaucoma patients." (PMID 20057908, 2009). "We screened the entire coding region of CYP1B1 in 23 congenital glaucoma patients by using primers described elsewhere." (PMID 20057908, 2009). "Nevertheless, this study provides an essential profile of CYP1B1 and its highly associated missense variants with the PCG that can be potentially used as diagnostic markers and will be helpful for the management of primary congenital glaucoma studies." (PMID 36518267, 2022). "The high percentage (9/25=36%) of mutations in CYP1B1 found in non-consanguineous patients with congenital glaucoma mandates genetic testing." (PMID 23922489, 2013). "Hollander and coworkers correlated CYP1B1 mutations with the degree of angle dysgenesis observed histologically, as well as disease severity in terms of age at diagnosis and difficulty in controlling IOP in six congenital glaucoma patients." (PMID 22128238, 2011). "This will further help in the elucidation of the structure-function relationship of CYP1B1 and hence may lead to the development of novel therapeutics in management of congenital glaucoma in familial cases." (PMID 19536304, 2009). "However, it has been reported that patients with CYP1B1 mutations need more surgical procedures to control intraocular pressure than individuals with congenital glaucoma without CYP1B1 mutations." (PMID 22128238, 2011). "Thus, it is important to screen other loci for involvement in congenital glaucoma in cases which are negative or heterozygous for CYP1B1 mutations to have a better insight in to disease pathogenesis." (PMID 21031026, 2010). "Thus, it is important to screen other loci for involvement in congenital glaucoma in cases which are either negative or heterozygous for CYP1B1 mutations to have a better insight in disease pathogenesis." (PMID 21031026, 2010). "The intricate genetic landscape of Primary Congenital Glaucoma (PCG) was further complicated by interactions between TEK and CYP1B1 genes, hinting at a digenic mode of inheritance in specific cases." (PMID 38694874, 2024). "Digenic inheritance involving CYP1B1 and MYOC has been reported in early-onset congenital glaucoma and PCG." (PMID 30657791, 2019). "In addition to CYP1B1, other genes such as LTBP2, MYOC, TEK, FOXC1 and CPAMD8 are involved in a few congenital glaucoma cases." (PMID 34208498, 2021). "We show that cyp1b1 inactivation does not mimic congenital glaucoma but leads to adult-onset and variable craniofacial alterations." (PMID 34208498, 2021). "The current results suggest that congenital glaucoma, whether CYP1B1 related or not, and early adult-onset POAG may be different manifestations of the same disease continuum with contrasting severity." (PMID 28264060, 2017). "In the gene knockout groups with genes related to congenital glaucoma, GMDS, FOXC1, LTBP2, TEK, and CYP1B1, no distinct patterns were observed in the transcriptome of these gene knockout groups." (PMID 38272457, 2024).
lung cancer (31 papers, 2006 to 2025). A malignant neoplasm involving the lung. "There are many scientific reports indicating a link between the presence of CYP1B1 polymorphisms and the risk of lung cancer." (PMID 38928381, 2024). "This article presents the principle of lung cancer screening based on CYP1B1 gene polymorphism and polarization imaging and explores the diagnosis and treatment of non-EGFR mutant lung cancer." (PMID 37791062, 2023). "The relevance of the IDO-AHR-IL-6-STAT3 transcriptional circuit is underscored by the finding that high expression of its members IDO, STAT3 and the AHR target gene CYP1B1 is associated with reduced relapse-free survival in lung cancer patients." (PMID 24657910, 2014). "Most importantly, high IDO1, STAT3 and CYP1B1 expression was associated with reduced relapse-free survival in lung carcinoma patients." (PMID 24657910, 2014). "The association of SNPs in CYP1B1 with the increased risk of ovarian, endometrial, renal, and prostate cancers as well as smoking-related lung cancer has been reported in the Caucasian and the Japanese populations." (PMID 24151610, 2013). "Previous results on CYP1B1 polymorphisms and lung cancer have been limited to the four non-synonymous SNPs rs10012, rs1056827, rs1056836 and rs1800440." (PMID 19479063, 2009). "Additionally, a study on squamous cell carcinoma of the respiratory tract found a high frequency of the CYP1B1*2 355T allele in patients with lung cancer, suggesting that the presence of this allele increased the risk for developing lung cancer." (PMID 25299224, 2014). "The results suggest that the CYP1B1 polymorphism may contribute to increased susceptibility to early-onset lung cancer in women." (PMID 24212786, 2011). "Other studies have also reported such an observation, thereby demonstrating a high frequency of CYP1B1 expression in patients with advanced grades of non–small cell lung cancer and renal cancer." (PMID 34636736, 2021). "A high frequency of CYP1B1 expression has been reported in cancers of the brain, breast, prostate, colon, bladder, muscle (rhabdomyosarcoma), ovary, and lungs (non–small cell lung cancer)." (PMID 34636736, 2021). "CYP1B1 differentially methylated effects have been reported for smoking, for lung cancer, and for age at cancer diagnosis in non-small cell lung carcinoma (NSCLC) samples." (PMID 30342560, 2018). "Levels of CYP1B1 mRNA vary widely from decreased levels in mesothelioma and melanoma to increased levels in prostate and nonsmall cell lung cancer." (PMID 24151610, 2013). "Moreover, carvedilol inhibits cytochrome P450 1B1 (CYP1B1) in different lung cancer cells in vitro and in vivo." (PMID 37370809, 2023). "Simultaneously, CYP1B1 protein was observed overexpressed in the livers of patients in many cancers (including lung cancer), which was strongly implying that CYP1B1 may have relevance with cancers process." (PMID 28377924, 2017). "Before us, there was no report on the influence of CYP1B1 gene polymorphisms on lung cancer prognosis." (PMID 28377924, 2017). "In this large population-based case-control study of lung cancer we have observed that EPHX1, CYP1A1, CYP1B1 and CYP2A6 genes may play a role in lung cancer susceptibility." (PMID 19479063, 2009). "The CYP1B1 gene is known to be highly expressed in lung tissues of lung cancer patients." (PMID 19479063, 2009). "We selected 7 SNPs in CYP1B1 gene, 6 of which not previously studied in association with lung cancer." (PMID 19479063, 2009). "Thus, it was suggested that CYP1B1 and CYP2A13 genotypes may contribute to individual susceptibility to early-onset lung cancer in women." (PMID 34830188, 2021). "Next, we detected the expression of AhR pathway genes (IDO1, AhR, CYP1A1, and CYP1B1) in SARS-CoV-2–infected and mock-infected human lung cancer cells (H1299 and Calu-3)." (PMID 37256962, 2023).
lung cancer (continued). "Interestingly, women seem to be prone to an increased risk of early-onset lung cancer if they are carriers of the minor allele of CYP1B1 SNP rs1056836 (10042C>G/T), but a nonsignificant increased risk was observed for the carriers of the minor allele of CYP2A13 SNP rs1709084 (13103A>G)." (PMID 34830188, 2021). "The simultaneous induction of CYP1A1 and CYP1B1 in both types of lung cells obtained from BAL and pulmonary epithelial cells after smoking cigarettes, as found in the present study, may therefore enhance an individual susceptibility for chemically induced lung cancer." (PMID 17107849, 2006). "Cigarette smoke was reported to induce CYP1A1 and CYP1B1 expressions in lung tissue of smokers and of lung cancer patients (both smokers and non-smokers), which correlates with increased levels of BPDE and DNA adducts." (PMID 38982523, 2024). "Our data do not support proposed associations between lung cancer and EPHX1 rs2234922, CYP1B1 rs1800440, and MPO rs2333227." (PMID 19479063, 2009).
Obesity (27 papers, 2016 to 2025). Accumulation of substantial excess body fat. "CYP1B1 is an important gene associated with obesity, based on a review of 49 obesity-related genome-wide sequencing studies covering 16,186 genes." (PMID 36518674, 2022). "In agreement with this, a study on transgenic CYP1B1 deficient mice that were fed with a high-fat diet (HFD) showed improved glucose intolerance with potentially lowered obesity compared with wild-type animals." (PMID 36418969, 2022). "Elevated CYP1B1 is associated with obesity and metabolicsyndrome, playing an important role in increasing adiposity and insulinresistance." (PMID 32999709, 2020). "In addition, Cyp1b1 deficiency has been shown to protect mice from high‐fat diet–induced obesity, thereby further underscoring its critical role in the regulation of lipid metabolism." (PMID 40971194, 2025). "Moreover, CYP1B1 deficiency attenuated HFD‐induced obesity and improved glucose tolerance due to the reduced expression of different adipogenic genes such as PPARγ, CD36, FAS, and SCD‐1 and increased expression of genes involved in lipolysis." (PMID 39806854, 2025). "Furthermore, Cyp1b1 deficiency has been shown by other groups to attenuate high‐fat diet‐induced obesity and improve glucose tolerance." (PMID 40971194, 2025). "Whether the association of leptin, CYP1B1 and AhR ligands is correlated in adult obesity, in association with a decreased CD8+ T cell and NK cell cytotoxicity, as some data could suggest, will be important to determine." (PMID 33375613, 2020). "The expression of CYP1B1 influenced the development of obesity, in CYP1B1-null mice, the expression level of SCD1 was reduced, which inhibited obesity and thus affected lipid metabolism." (PMID 39944639, 2025). "For example, variants in the fat mass and obesity-associated (FTO) gene and the cytochrome P450 1B1 (CYP1B1) gene have been linked to blood pressure regulation and hypertension development in various populations." (PMID 41154871, 2025). "In particular, ADAM metallopeptidase domain 12 (ADAM12) and cytochrome P450 family 1 subfamily B member 1 (CYP1B1) were found to be upregulated in obesity and their silencing reduced RCC cell invasiveness." (PMID 39806854, 2025). "CYP1B1 is involved in obesity, hypertension, adipogenesis, and atherosclerosis via regulating endogenous metabolic pathways including the metabolism of steroid hormones, fatty acids, and vitamins." (PMID 37639183, 2024). "This systemic Cyp1b1-/- mouse fully reproduces the obesity suppression of the classic exon 3 disruption." (PMID 38069208, 2023). "The mRNA expression of a cytochrome P450 gene CYP1B1, ALOX5 (which encodes 5-LOX), and PTGS1 (which encodes COX-1) was upregulated in individuals living with obesity." (PMID 35247847, 2022). "CYP1B1 is involved in metabolism of steroids and fatty acids; its knockdown in mice reduces development of obesity in response to a high-fat diet." (PMID 36589428, 2022). "Among them, PCK1 is the rate-limiting enzyme that regulates gluconeogenesis, and CYP1B1 plays an important role in estrogen metabolism, probably corresponding to the phenotype of obesity and hormonal disturbance in PCOS patients, respectively." (PMID 34113617, 2021). "CYP1B1-null mice display attenuated high-fat diet (HFD)-induced obesity and improved glucose tolerance related to increased fatty acid oxidation markers." (PMID 32349335, 2020). "The upregulation of CYP1B1 in obesity is likely tocontribute to an increase in the presence of 16α-hydroxyestrogens that have alsobeen associated with PAH." (PMID 32999709, 2020). "They determined that by comparing with wild type counterparts, CYP1B1 null mice attenuated HFD-induced obesity and improved glucose tolerance." (PMID 35515562, 2019). "They described that CYP1B1-ko resulted in attenuating HFD-induced obesity, enhanced glucose tolerance and prohibited liver steatosis." (PMID 35515562, 2019).
Obesity (continued). "For example, CYP1B1 deletion has been reported to diminish adult obesity and liver inflammation." (PMID 41212877, 2025). "In addition, disruption of the CYP1B1 gene has demonstrated extensive protection against obesity and steatotic hepatitis." (PMID 36418969, 2022). "Since TSPYL1 knockdown in hepatic cells resulted in increased CYP1B1 and decreased CYP7A1 expression, we asked whether TSPYL1 expression might be associated with obesity and/or plasma cholesterol concentrations in humans." (PMID 36518674, 2022). "CYP1B1 also plays an important role in adipogenesis and obesity." (PMID 32999709, 2020). "CYP1B1 modulators could also be considered as therapeutic agents to protect againstthe metabolic effects of obesity." (PMID 32999709, 2020). "As obesity in male mice may be uniquely driven by CYP1B1-induced E2 metabolism we focused on the ob/ob males to investigate this further." (PMID 30923189, 2019). "However, recently there are some reports highlighting CYP1B1 as a potential regulator in energy homeostasis and adipogenesis thus promoting obesity and hypertension as well." (PMID 35515562, 2019). "Inhibition of CYP1B1 with TMS also reversed the obesity-induced increase in RVSP in males." (PMID 30923189, 2019). "Studies have reported that with high-fat diet-induced obesity, mice lacking CYP1B1 were leaner and more resistant to obesity than the control." (PMID 40917351, 2025). "The mRNA expression of CYP1B1, ALOX5 and PTGS1 were upregulated in individuals with obesity." (PMID 38024342, 2023). "In addition, the activation of AHR/CD36 pathway promotes hepatic steatosis in mice, while inhibiting the activity of AHR and altering the expression levels of CYP1B1, PPARα, and SCD-1 that attenuate the diet-induced obesity and hepatic steatosis in mice." (PMID 34722615, 2021). "Changes in CYP1B1-mediated estrogen metabolism in obesity have not been wellstudied." (PMID 32999709, 2020). "Till date a lot of research work has been done evaluating the role of CYP1B1 in the progression of PCG and cancer, however, there is still a large gap in the available literature describing its part in the development of diseases like hypertension, obesity and type 2 diabetes as well." (PMID 35515562, 2019). "This suggests that CYP1B1 activity may not drive the obesity-induced changes in RVSP in females." (PMID 30923189, 2019).